JUNB (JunB proto-oncogene, AP-1 transcription factor subunit)
Diseases named in the same sentence as JUNB in open-access papers (continued):
Sharing a sentence is not in itself a finding about the gene and the disease.
lung carcinoma (continued). "Further studies indicated that METTL3 m6A methyltransferase regulates JunB mRNA and c-Jun protein expression at 3’-UTR in TGF-β1 induced EMT in lung cancer, respectively." (PMID 37731821, 2023). "JUNB and CXCR4 are expressed in lung cancer patients and their expression correlates with worse prognosis." (PMID 36612166, 2022). "In summary, we demonstrated the different modes of m6A regulation for JUN and JUNB TFs, which play an integral role in the EMT-inducing gene regulation during TGF-β-dependent EMT of lung cancer cell lines." (PMID 36183833, 2022). "We have so far demonstrated that the m6A regulation of JUN and JUNB by METTL3 plays a critical role in the expression levels of them, thereby affecting the EMT-inducing gene expression program of A549 and LC2/ad lung cancer cells." (PMID 36183833, 2022). "In this study, we found that knockdown of JUN and JUNB affected the expression of epithelial and mesenchymal marker genes during TGF-β-dependent EMT of A549 and LC2/ad lung cancer cells." (PMID 36183833, 2022). "Previously, we have shown that JUNB is one of the important TFs regulated by METTL3 m6A methyltransferase during TGF-β-induced EMT of A549 and LC2/ad lung cancer cell lines." (PMID 36183833, 2022). "To validate the involvement of JUN family TFs in TGF-β-induced EMT of lung cancer cells, we first examined the changes in expression of JUN, JUNB, and JUND by TGF-β treatment." (PMID 36183833, 2022). "A number of established lung cancer oncogenes have also been included in the classifier, such as IL1R2, JUNB, EGFR, SOX9, FOSB, and JUND." (PMID 27935865, 2017). "For example, the overexpression of m6A methyltransferase METTL3 could regulate the expression of the JUNB gene, which contributed to the epithelial-mesenchymal transition (EMT) in lung cancer." (PMID 37047493, 2023). "Although the number of patients in this manuscript is relatively small, it provides the basis for the importance of JUNB and CXCR4 expression in lung cancer patients’ CTCs as an indication of patients’ poor survival and further supports their role in metastasis, confirming related studies." (PMID 36612166, 2022). "Both JUNB and CXCR4 were expressed in the vast majority of lung cancer patients." (PMID 36612166, 2022). "In the present study, we evaluated the expression of JUNB and CXCR4 in circulating tumor cells (CTCs) of lung cancer patients and investigated whether these proteins have prognostic clinical relevance." (PMID 36612166, 2022). "Over-expression of JunB Proto-oncogene increases the involvement of EMT in the invasion and metastasis of lung cancer; Colony-stimulating factor 1 (CSF1) increases the proliferation and invasion of lung cancer cells." (PMID 35910766, 2022). "Our results showed that both JUNB and CXCR4 were overexpressed in CTCs from lung cancer patients." (PMID 36612166, 2022). "Studies have shown that JUNB and CXCR4 contribute to cell proliferation, migration and invasion, hence claiming an important role in tumor progression and metastasis, in various cancer types, including lung cancer." (PMID 36612166, 2022). "Furthermore, both proteins were correlated with poor survival in non-small-cell lung cancer patients, while only CXCR4 was associated with worse survival in small-cell lung cancer patients, suggesting that JUNB and CXCR4 are potentially important prognostic biomarkers for lung cancer." (PMID 36612166, 2022). "In contrast, JUNB was necessary and sufficient for EMT in MCF10A cells, but not in A549 lung cancer cells, indicating cell-type-specificity of JUNB EMT-regulatory capacity." (PMID 36672507, 2023). "In this study, we discovered the m6A RNA modification–dependent regulation of JUN and JUNB TFs, which plays an essential and nonredundant role in gene expression program during TGF-β-induced EMT of A549 and LC2/ad lung cancer cells." (PMID 36183833, 2022).
lung carcinoma (continued). "Quantitative RT–PCR (QRT–PCR) revealed that the expressions of JUN and JUNB but not of JUND mRNA were increased by TGF-β in A549 and LC2/ad lung cancer cell lines." (PMID 36183833, 2022). "To validate the involvement of YTHDF3 and IGF2BP1 in the regulation of JUN and JUNB expression, we confirmed the knockdown effects in protein and mRNA expression in A549 and LC2/ad lung cancer cells with or without TGF-β treatment." (PMID 36183833, 2022). "Both JUNB and CXCR4 have been related to metastasis, while to date, evaluation of both JUNB and CXCR4 in lung cancer patients’ CTCs has not been presented." (PMID 36612166, 2022).
COVID-19 (13 papers, 2020 to 2024). A disease caused by infection with severe acute respiratory syndrome coronavirus 2. "In addition, the combination of SAMD9, GZMB, JUNB, and NR4A1 presented excellent diagnostic value in COVID-19." (PMID 38384322, 2023). "Similarly, we found the relevant evidence of alteration or association of transcription factors CENPA, DDIT3, JUNB, TFDP1, ZBTB16, ZNF467 for the alteration of diverse cellar process and function to develop the COVID-19 pathogenesis and associated respiratory disorders." (PMID 38365632, 2024). "Specifically, the IRF7 (+) regulon was activated in severe COVID-19, whereas FOS (+) and JUNB (+) regulons were activated in healthy neutrophils." (PMID 38612651, 2024). "Downregulation of JUNB and LEF1, and upregulation of RUNX3 was observed in all three ILC subsets from COVID-19 patients." (PMID 39026668, 2024). "The differential expression analysis identified six differentially expressed genes (DEGs) shared by myasthenia gravis (MG) and COVID-19, namely SAMD9, PLEK, GZMB, JUNB, NR4A1, and NR1D1." (PMID 38384322, 2023). "Patients with COVID-19 showed downregulation of genes involved in the AP-1 transcription factor pathway (including JUN, JUNB, JUND, and FOSB) as well as HLA genes (including HLA-E, HLA-DRB1, HLA-DRA, and HLA-DPB1)." (PMID 36992700, 2023). "In the present study, we identified six shared genes (SAMD9, PLEK, GZMB, JUNB, NR4A1, and NR1D1) of MG and COVID-19 patients through bioinformatic analysis." (PMID 38384322, 2023). "We identified FOS, NFKB1, JUNB, JUN, and NFKB1A as core target genes of quercetin for the treatment of COAD/COVID-19." (PMID 36249762, 2022). "By constructing a protein-protein interaction (PPI) network, we ascertained FOS, NFKB1, NFKB1A, JUNB, and JUN as possible core target genes of quercetin for the treatment of COAD/COVID-19." (PMID 36249762, 2022). "In addition, we found that some TFs were differentially expressed in severe COVID-19, including TF upregulations of IRF7, SP100, HMGB2, and BCL6, and downregulations of FOS and JUNB." (PMID 38612651, 2024). "FOS, JUN, NFKB1, JUNB, and NFKB1A had the highest degree values, so we concluded that these genes might be the core target genes of quercetin for the treatment of COAD/COVID-19." (PMID 36249762, 2022). "Notably, the mitogen-activated protein kinase (MAPK) pathway (i.e., FOS, JUN, JUNB, and DUSP1) was greatly suppressed in all recovered patients compared with that in the HCs, which suggested that inhibition of the MAPK signaling pathway is a recovery sign of COVID-19 patient." (PMID 37853311, 2023).
lymphoma (13 papers, 2007 to 2025). A malignant (clonal) proliferation of B- lymphocytes or T- lymphocytes which involves the lymph nodes, bone marrow and/or extranodal sites. "In human lymphoma cells, JunB has been shown to protect against oxidative stress-induced cell death." (PMID 39822976, 2025). "Previous studies have indicated that JUNB is a critical determinant of myelopoiesis and several lymphomas." (PMID 37337631, 2023). "Intriguingly, aberrantly expressed JunB facilitates the progression of ccRCC, multiple myeloma, and several lymphomas through transcriptionally promoting the production of chemokines, inflammatory cytokines, and growth factors within the TME." (PMID 37731821, 2023). "A growing number of studies found that JunB is a potential oncogene in lymphoma, including Hodgkin lymphoma (HL) and anaplastic large cell lymphoma (ALCL)." (PMID 37731821, 2023). "JunB has been shown to be protective against mitochondrial stress in human lymphoma cells, and structurally, JunB can localize in mitochondria." (PMID 36276935, 2022). "There is also evidence that c-Jun and JunB have overlapping functions with respect to promoting proliferation and/or growth in these lymphomas." (PMID 33413671, 2021). "We further investigated the effect of c-Jun and JunB knock-down on proliferation in another CD30–positive lymphoma, anaplastic lymphoma kinase-positive, anaplastic large cell lymphoma (ALK+ ALCL)." (PMID 30375407, 2018). "Elevated expression and/or the constitutive activation of c-Jun and JunB are common to other CD30–positive lymphomas including ALK+ ALCL19,20,22,23, ALK− ALCL20,24, cutaneous ALCL20,24,25, and CD30–positive diffuse large B cell lymphoma." (PMID 30375407, 2018). "The mean JUNB intensity in JunB wildtype tumors was about twice as high as the levels in JunB heterozygote lymphomas, which exactly reflected the results obtained from total protein lysates and Western blots." (PMID 25013898, 2014). "The intensity of JUNB staining was strong in the JunB+/+, intermediate in JunB+/Δ and undetectable in JunBΔ/Δ lymphomas (except for stromal cells)." (PMID 25013898, 2014). "After subtraction of the stroma background level of JUNB expression determined in the NPM-ALK/JunBΔ/Δ tumors, the relative expression levels were approximately two times higher in NPM-ALK/JunB wildtype cells compared to the hemizygous JunB lymphoma samples." (PMID 25013898, 2014). "In a mouse model of this disease, the AP-1 members Jun and JunB were found to promote the expression of PDGF-B in the lymphoma cells." (PMID 24359404, 2013). "JunB also influences phenotypic characteristics of this lymphoma through promoting the transcription of CD30 and the Granzyme B serine protease." (PMID 22852078, 2012). "CD30 signalling also activates MEK/ERK/JunB signalling in this lymphoma to further promote CD30 expression." (PMID 22852078, 2012). "Additionally, research in lymphoma suggests that inhibiting mTOR can downregulate JunB protein levels and reduce cell proliferation, indicating that JunB is a crucial target of mTOR." (PMID 40918148, 2025). "Importantly, the fact that CD30 is both a target and regulator of JunB means that a positive feedback loop is generated that ensures high levels of CD30 and JunB in these lymphomas." (PMID 33413671, 2021). "Taken together, these results show that while a G0/G1 cell cycle defect was associated with reduced JunB expression in both cHL and ALK+ ALCL cell lines, the molecular basis for this defect may differ between these lymphomas." (PMID 30375407, 2018). "Furthermore, we used this same approach to investigate whether stable c-Jun or JunB knock-down results in a similar phenotype in another CD30-positive lymphoma, ALK+ ALCL." (PMID 30375407, 2018).
lymphoma (continued). "cHL and the other CD30–positive lymphomas are characterized by the elevated expression and/or constitutive activation of the activator protein-1 (AP-1) family transcription factors, c-Jun and JunB; however, the specific roles they play in the pathobiology of cHL are unclear." (PMID 30375407, 2018). "Here again, expression of cFOS, MXD1, JUNB, cJUN, and DUSP1 was significantly higher (3.7 fold, 7.1 fold, 3.1 fold, 3.4 fold and 9.1 fold, respectively) in lymphomas with high cytoplasmic NR4A1 content (p < 0.036)." (PMID 30266952, 2018). "Similar to other CD30+ lymphomas, CTCLs, including cutaneous ALCL and Lymphomatoid Papulosis (LyP), show abnormal JUNB expression which correlates with both CD30 and MAPK/ERK pathway activity." (PMID 29597249, 2018). "As well, a lack of GSK3β activity in this lymphoma has been argued to lead to a failure of JunB to be phosphorylated, and subsequently targeted for degradation, by the Fbxw7 E3 ubiquitin ligase." (PMID 33413671, 2021). "This indicates that while the role of JunB in promoting proliferation is largely similar in cHL and ALK+ ALCL cell lines, the importance of c-Jun in regulating proliferation differs between these two CD30–positive lymphomas." (PMID 30375407, 2018).
anaplastic large cell lymphoma (11 papers, 2017 to 2023). Anaplastic large cell lymphoma (ALCL) is a rare and aggressive peripheral T-cell non-Hodgkin lymphoma, belonging to the group of CD30-positive lymphoproliferative disorders, which affects lymph nodes and extranodal sites. "c-Jun and JunB are highly expressed in many tumors, such as colon cancer, Hodgkin’s disease, melanoma, and anaplastic large cell lymphoma tissue." (PMID 37483616, 2023). "The data of the current study are in line with previous studies reporting the role of JUNB in cancer progression, such as Hodgkin’s disease and anaplastic large cell lymphomas." (PMID 31370904, 2019). "Primary cutaneous T-cell lymphoma and anaplastic large cell lymphoma are closely related to JUNB." (PMID 37221625, 2023). "Moreover, overexpression of JUNB has been shown to contribute to neoplastic development in several human cancers, including anaplastic large cell lymphoma (ALCL), certain Hodgkin’s lymphomas, and breast and stomach cancers." (PMID 36494864, 2022).
multiple myeloma (10 papers, 2021 to 2025). "Elevated JUNB was additionally associated with therapy resistance in Multiple Myeloma." (PMID 40701988, 2025).
prostate carcinoma (10 papers, 2008 to 2026). A carcinoma that arises from epithelial cells of the prostate gland. "Our data revealed that loss of either JunB or Fos in the context of Pten loss drives prostate cancer progression to invasive disease." (PMID 34548912, 2021). "We have shown that loss of JunB or Fos in combination with Pten-deficiency drives prostate cancer progression to an invasive disease." (PMID 34548912, 2021). "In the context of prostate cancer (PCa), JUNB has been reported to exhibit mostly tumor-suppressing functions." (PMID 41020863, 2025). "In the prostate cancer cell line PC-3, JUNB has been indicated to promote migration and antagonize the opposite function of JUND." (PMID 38727318, 2024). "JUNB, a member of the JUN family, is associated with poor prognosis in human gastric cancer and prostate cancer cell lines." (PMID 39409043, 2024). "We analyzed expression of FOS and JUNB in human prostate cancer datasets and observed decreased expression in advanced stages." (PMID 34548912, 2021). "Decreased expression of other AP-1 subunits and pathways has been shown in advanced prostate cancer for JUNB and the c-Jun N-terminal kinase (JNK)." (PMID 34548912, 2021). "Two possible downstream effects were proposed for JUNB: the induction of p16 associated cell cycle arrest and the suppression of MMP2, which is involved in the progression of prostate cancer." (PMID 28005952, 2016). "Additionally, activated JUNB effectively hinders the malignant progression of prostate cancer as measured by invasion and metastasis." (PMID 38727318, 2024). "In addition, a full transcriptome analysis showed that JUNB is present in severely affected patient groups and metastatic lesions, which are thought to play a role in prostate cancer progression." (PMID 38727318, 2024). "Studies have shown that the combination of JUNB and miR-95t could act as a tumor promoter to promote proliferation and invasion in prostate cancer." (PMID 37479694, 2023). "Therefore JUNB could serve as a biomarker for prostate cancer and for evaluating whether a given primary tumor has the potential to progress to metastatic phases." (PMID 28005952, 2016). "A 5-gene recurrence predictor of prostate cancer contains KLF6, three common ARACNe-based predictions between MYC and KLF6 (FOS, JUNB and ZFP36), and PPFIA3, which is functionally related to another predicted target of KLF6 (PPFIBP2)." (PMID 18190704, 2008). "Hence, androgen-induced interactions between AR and JUNB or ERF may confer growth inhibitory actions that are conserved across breast and prostate cancer contexts, but this requires future investigation." (PMID 38317241, 2024).
pancreatic cancer (9 papers, 2014 to 2025). "JUNB gene encodes a transcriptional factor, and it regulated the expression of FAM83A, a gene significantly elevated in human and murine pancreatic cancers." (PMID 34055623, 2021). "For instance, a recent murine experimental model has demonstrated that IFN-γ and TNF-α produced by Th1 cells are capable of inducing prolonged senescence in pancreatic tumors, by inducing expression of the transcription factors JUNB and INK4A." (PMID 24672527, 2014). "In the pancreatic cancer cell line PANC1, JUNB and four of the other eight genes analyzed showed a positive TGFβ1 response." (PMID 36672507, 2023). "In KC, KC;iASPPΔ8/Δ8, and KPC tissues, JunB, JunD and nuclear p-p65RelA are not expressed in morphologically normal acini but are readily detectable in metaplastic lesions and pancreatic cancer cells." (PMID 37270580, 2023).
gastric cancer (8 papers, 2021 to 2025). A primary or metastatic malignant neoplasm involving the stomach. "JUNB is overexpressed in oxaliplatin-resistant gastric cancer cells, and its upregulation is associated with poor prognosis in gastric cancer patients, which is validated by our tissue microarray data." (PMID 37337631, 2023). "There is some evidence for a role of AP-1 factors in chemotherapy resistance: JUNB was shown to mediate oxaliplatin resistance in gastric cancer cells, by inducing DNA-repair-enzymes." (PMID 40701988, 2025). "This study provides evidence that JUNB mediates oxaliplatin resistance in gastric cancer by activating the MAPK pathway." (PMID 37337631, 2023). "While established mechanisms of OXA resistance in gastric cancer involve JUNB-mediated MAPK hyperactivation, EphA2-induced EMT, METTL3-dependent DNA repair/stemness maintenance, and LINC00641-regulated autophagy, our study reveals a distinct immunosuppressive axis mediated by OASL." (PMID 41271618, 2025). "Kaplan-Meier analysis further demonstrated that high expression of JUNB was correlated with worse overall survival (OS) and progression-free survival (PFS) for gastric cancer patients from the Zhongshan-GC dataset." (PMID 37337631, 2023). "We obtained 43 DEGs with the adjusted p < 0.05 and | log2 FC)|>1, of which JUNB, ID1, CDKN1C, ID3, and BCAR3 were lowly expressed in gastric cancer tissues, and the remaining DEGs were highly expressed in gastric cancer tissues." (PMID 36467074, 2022). "Of note, pancancer analysis of anatomically distinct solid tumors suggested that c-JUN/JUNB and FOSL1/2 are bona fide canonical AP-1 TF configurations in mesenchymal states of lung, kidney, and stomach cancers." (PMID 34399888, 2021).